ALDH18A1 (aldehyde dehydrogenase 18 family member A1)
Diseases named in the same sentence as ALDH18A1 in open-access papers (continued):
Sharing a sentence is not in itself a finding about the gene and the disease.
prostate carcinoma (3 papers, 2015 to 2023). A carcinoma that arises from epithelial cells of the prostate gland. "By analyzing six primary prostate cancer specimens and eight prostate cancer cell lines, it was indicated that ALDH isoforms with higher expression levels were ALDH3A2, ALDH4A1, ALDH7A1, ALDH9A1, and ALDH18A1." (PMID 37686694, 2023). "Furthermore, it has been demonstrated that ALDH4A1 and ALDH9A1 are the primary enzyme isoforms responsible for ALDEFLUOR activity in prostate cancer tissues, whereas ALDH3A2 and ALDH18A1 are the predominant enzyme isoforms in non-tumor tissues and high-grade prostate intraepithelial neoplasia." (PMID 37686694, 2023).
Autosomal recessive cutis laxa type 3A (2 papers, 2014 to 2021). "Autosomal recessive cutis laxa type 3A is caused by mutations in ALDH18A1, a gene encoding the mitochondrial enzyme Δ1-pyrroline-5-carboxylate synthase (P5CS)." (PMID 25077174, 2014).
endometrial cancer (2 papers, 2022 to 2024). Primary or metastatic malignant neoplasm involving the endometrium (mucous membrane that lines the endometrial cavity). "According to the Human Protein Atlas, a high expression of ALDH18A1 in endometrial cancer was associated with a better prognosis, reflecting a greater probability of survival." (PMID 38893151, 2024). "In our understanding, in endometrial cancer the ALDH isoform ALDH18A1 can be a promising prognostic factor." (PMID 38893151, 2024). "Moreover, it was possible to identify three proteins as potential biomarkers for endometrial cancer, namely, ALDH18A1, SdhA, and UBAP2L." (PMID 38893151, 2024). "Moreover, ALDH18A1 isoform seems to be the most inhibited ALDH isoform in endometrial cancer, and a promising prognostic biomarker." (PMID 38893151, 2024). "SHetA2 treatment of endometrial cancer cells disrupted mortalin binding to metabolic enzymes, aldehyde dehydrogenase 18 family member A1 (ALDH18A1), cytidine triphosphate synthetase (CTPS), malate dehydrogenase (MDH1), and enoyl coenzyme A hydratase, short chain, 1, mitochondrial (ECHS1)." (PMID 35281109, 2022). "Additionally, the isoform ALDH18A1 was identified as the most abundant ALDH isoform in the proteomic profile of both endometrial cancer cell lines and one of the most down-regulated proteins upon DEAB treatment, this isoform being considered the most inhibited." (PMID 38893151, 2024). "Proteomic analysis revealed 105 common proteins altered in ECC-1 and RL95-2 cells upon DEAB treatment, suggesting ALDH18A1, SdhA, and UBAP2L as potential markers for endometrial cancer." (PMID 38893151, 2024). "The proteomic profiling of endometrial cancer cell lines revealed that ECC-1 and RL95-2 shared the ALDH isoforms ALDH3A1, ALDH3A2, ALDH3B1, ALDH3B2, ALDH7A1, ALDH9A1, and ALDH18A1 in their proteome." (PMID 38893151, 2024). "Furthermore, ALDH18A1, SdhA, and UBAP2L should be explored as novel molecular targets for endometrial cancer." (PMID 38893151, 2024). "Additionally, DEAB modulates the expression of certain proteins, namely, ALDH18A1, SdhA, and UBAP2L, identified in endometrial cancer, which might be promising prognostic and therapeutic targets." (PMID 38893151, 2024).
glioma (2 papers, 2021 to 2022). A benign or malignant brain and spinal cord tumor that arises from glial cells (astrocytes, oligodendrocytes, ependymal cells). "Analysis of the TCGA dataset showed that ALDH16A1, ALDH3B1, ALDH1A3, ALDH3A1, ALDH7A1 were significantly increased in IDH wildtype gliomas, while ALDH2, ALDH6A1, ALDH5A1, ALDH1A1, ALDH1L2, ALDH18A1, ALDH1B1 expression were higher in IDH mutant gliomas than IDH wildtype gliomas." (PMID 35116021, 2021).
microcephaly (2 papers, 2021 to 2025). A congenital or acquired developmental disorder in which the circumference of the head is smaller than normal for the person's age and sex. "Mutations in the aldehyde dehydrogenase 18 family member A1 (ALDH18A1) gene result in delta‐1‐pyrroline‐5‐carboxylate synthetase (P5CS) deficiency, were known to cause a condition presenting some phenotypic resemblance with SPG9, including a neurodevelopmental syndrome with microcephaly." (PMID 39932116, 2025).
asthma (1 paper, 2022). "We found PDCD11 was negatively associated with asthma-related TFs, including WT1, ZEB1, and RERE; ALDH18A1 was negatively associated with WT1 and RERE; SEC61A1 was negatively related with WT1 and ZEB1." (PMID 35169275, 2022). "Hence, PDCD11, ALDH18A1, and SEC61A1 may play a role in the development of asthma through transcriptional regulation-related mechanisms." (PMID 35169275, 2022).
Down syndrome (1 paper, 2023). "AD and Down syndrome were also linked to ALDH18A1 mutations." (PMID 37628788, 2023).
Epileptic encephalopathy (1 paper, 2024). A condition in which epileptiform abnormalities are believed to contribute to the progressive disturbance in cerebral function. "Three (3%) patients had status epilepticus at onset and two (2%) sisters, harbouring a compound heterozygous variant in the ALDH18A1 gene, had developmental/epileptic encephalopathy with spike wave activation in sleep (DEE-SWAS) at onset." (PMID 38279250, 2024).
glioblastoma (1 paper, 2025). The most malignant astrocytic tumor (WHO grade IV). "Moreover, silencing ALDH18A1 under hypoxic conditions prolongs the overall survival of patients with glioblastoma." (PMID 41573681, 2025).
learning disabilities (1 paper, 2019). "Although Aldh18a1 dysregulation has been linked with learning disabilities and neurodevelopmental deficits, hippocampal dysregulation in the context of FASD remains unknown." (PMID 31140755, 2019).
Lipedema (1 paper, 2022). Disorder of adipose tissue characterized by symmetric and bilateral enlargement of the lower extremities due to abnormal deposition of subcutaneous fat often in obese women. "Because lipedema is associated with hypermobile joints, a connective tissue disease, and is found in Williams syndrome, ALDH18A1 should not be ruled out as a gene that influences lipedema." (PMID 35207755, 2022).
neurocutaneous syndrome (1 paper, 2022). A group of disorders characterized by ectodermal-based malformations and neoplastic growths in the skin, nervous system, and other organs. "Pathogenic mutations in the P5CS gene (ALDH18A1) lead to neurocutaneous syndrome and skin relaxation connective tissue disease in humans, and P5CS deficiency seriously damages the ability to resist adversity in plants." (PMID 35286254, 2022).
renal carcinoma (1 paper, 2025). A carcinoma arising from the epithelium of the renal parenchyma or the renal pelvis. "While ALDH18A1 has been previously implicated in many cancers, including renal cancer, this study uniquely highlights its role as part of the IR-induced SASP, connecting its upregulation to SASP-driven tumorigenesis." (PMID 39858632, 2025). "RCE cell-specific IR-induced SASP factors, such as ALDH18A1 (Log2 ratio 1.43) and ASPH (Log2 ratio 1.20), which are associated with a highly unfavorable prognosis in renal cancers, underscore the tumor-promoting potential of specific SASP factors." (PMID 39858632, 2025). "Statistical analysis revealed significant changes in ALDH18A1 expression in stage I vs. stage III and stage IV of renal cancer." (PMID 39858632, 2025). "This study offers a novel perspective by identifying ALDH18A1 and ASPH as integral components of the IR-induced SASP, establishing a previously unrecognized link between radiation-induced senescence and renal cancer progression." (PMID 39858632, 2025). "Both ALDH18A1 and ASPH exhibited stage-specific alterations in expression, highlighting their potential relevance to renal cancer progression." (PMID 39858632, 2025). "Highly expressed unfavorable SASP factors, such as ALDH18A1 and ASPH, were identified as key drivers of renal cancer." (PMID 39858632, 2025).
schizophrenia (1 paper, 2024). A major psychotic disorder characterized by abnormalities in the perception or expression of reality. "In contrast, the level of the proline synthesis enzyme PYCR1 was higher in schizophrenia patients, although two other proline synthesis enzymes, ALDH18A1 and PYCR2, exhibited slightly lower levels compared to healthy controls." (PMID 37815900, 2024).
tumor (42 papers, 2015 to 2025). "In the context of GC, both ODC1 and ALDH18A1 were abnormally expressed in tumor cell lines, and their expression was associated with multiple signaling pathways linked to disease progression." (PMID 41573681, 2025). "The transcriptomic analysis of four databases indicated that ALDH18A1 exhibited elevated expression in tumor cells and was linked to a reduced overall survival." (PMID 38970690, 2024). "Analysis of TCGA-KIRC cohort revealed that ALDH18A1 (P5CS) displayed elevated expression in tumor, and it was linked to shorter overall survival." (PMID 38970690, 2024). "RCC2 and ALDH18A1 high expression have been confirmed associated with tumor progression." (PMID 39908861, 2025). "First, the expression and biological functions of ODC1 and ALDH18A1 in tumor cells were confirmed through in vitro experiments, validation in several independent clinical samples has not yet been performed." (PMID 41573681, 2025). "Beyond its role in proline metabolism, ALDH18A1 also regulates glutamate metabolism, supporting tumor cell survival under metabolic stress." (PMID 39858632, 2025). "To further verify the expression of ALDH18A1 in different tumour cell lines, we downloaded cell line data from the Human Protein Atlas (HPA) database." (PMID 39051546, 2024). "As far as we are aware, our research marks the initial study to clarify the tumor-promoting function of ALDH18A1 (P5CS) in ccRCC, indicating its potential as a therapeutic target for this disease." (PMID 38970690, 2024). "Analysis of the FUSCC proteomic cohort revealed that ALDH18A1 was overexpressed in tumor, and once again, patients with elevated expression experienced a shorter OS." (PMID 38970690, 2024). "Increasing evidence has convincingly demonstrated that high expression of ALDH18A1 is a poor prognosis factor in different tumor types and increased proline biosynthesis is needed in cancer cells." (PMID 35169275, 2022). "ALDH18A1 and glutaminase protein are highly expressed in proliferative estrogen receptor positive (ER+) tumor cells compared to ER− cells." (PMID 35169275, 2022). "P5CS encoded by the aldehyde dehydrogenase 18A1 (ALDH18A1) gene in the proline cycle is also frequently elevated in HCC cells, and inhibiting its expression is associated with the retardation of tumor growth." (PMID 33477430, 2021). "The emerging evidences that increased PYCR1 and ALDH18A1 expression is a poor prognosis factor in different tumor types are robust and convincing, and suggest an increased need of Proline biosynthesis in cancer cells." (PMID 32500033, 2020). "Examination of the levels of all pathway proteins showed that mitochondrial proline biosynthesis pathway proteins, PYCR1, PYCR2 and ALDH18A1, are higher in tumor samples relative to normal tissue before and after treatment." (PMID 32960509, 2020). "For example, ALDH1A2, ALDH2, ALDH3A2 and ALDH9A1 were downregulated in all tumors among the 5 cancer types, whereas ALDH1B1, ALDH1L2 and ALDH18A1 were most upregulated in tumor parts." (PMID 29426835, 2018). "Transwell invasion assay revealed that knockdown of ALDH18A1 inhibited tumor cell invasion." (PMID 38970690, 2024). "The CCK-8 indicated knockdown of ALDH18A1 notably inhibited tumor cell proliferation." (PMID 38970690, 2024). "Indeed, the transcription factor c-Myc triggers expression of PYCR1 and ALDH18A1 in activated T lymphocytes, and there is evidence that proline metabolism contributes to the reprogramming of tumor-infiltrating macrophages." (PMID 33083024, 2020). "While ALDH18A1 was uniformly expressed across CCC and PCC tumors, ASPH expression was highly variable in both tumor types." (PMID 39858632, 2025).
tumor (continued). "Aldehyde dehydrogenase 18 family member A1 (ALDH18A1) is an ATP and NAD(P)H-dependent mitochondrial enzyme that promotes the synthesis of Pro and is upregulated in expression in various tumor cells." (PMID 40137165, 2025). "MS-based proteomic profiling of 113 FFPE tumor samples identified proline biosynthesis enzymes (PYCR1 and ALDH18A1) as markers of NAC resistance." (PMID 40790759, 2025). "MS-based profiling of tumor tissues identified enzymes involved in proline biosynthesis, namely PYCR1 and ALDH18A1, as markers of tumor relapse and poor OS." (PMID 40790759, 2025). "The use of databases, such as GENT2 and HPA, facilitated the further identification of ALDH18A1 and ASPH as critical SASP factors with unfavorable prognostic outcomes, highlighting their tumor-promoting potential." (PMID 39858632, 2025). "Correspondingly, ASS1, ALDH18A1 and PYCR, which regulate the synthesis of arginine and proline, also showed up-regulated expression in tumor and lymphoid tissues (Fig. 3a5, a6, a10, b3–b5)." (PMID 37164975, 2023). "Both low and high proliferative luminal tumours showed weak positive correlation between GLS2 protein and ALDH18A1 (p < 0.001), ALDH4A1 (p < 0.01), ATF4 (p = 0.001), PRODH (p < 0.001), SLC38A2 (p ≤ 0.001) and SLC7A11 (p < 0.001)." (PMID 34439127, 2021). "According to the classification of normal tissues and tumor tissues, it was found that the expression of ALDH3B1, ALDH18A1, etc., increased in a variety of cancers, but ALDH9A1 and ALDH2 showed the opposite trend in UCEC." (PMID 34670872, 2021). "Differential expression of seven of these genes (CFD, ALDH18A1, CHKA, DDIT3, ITGA6, PSPH and SQLE) was replicated in another set of 12 paired NASH-HCCs and adjacent non-tumor livers by RT-qPCR (all P < 0.05 by paired t test)." (PMID 30367044, 2018). "Furthermore, we examined the expression of several most well-known EMT-related genes (N-cadherin, SNAI1, Vimentin) and observed that ALDH18A1 knockdown suppressed the EMT process, indicating a reduced capacity for tumor migration." (PMID 38970690, 2024). "Likewise, up-regulation of L-Pro biosynthesis genes (ALDH18A1 and PYCR1) also reveals L-Pro starvation in tumor cells." (PMID 34458276, 2021). "A comprehensive study comparing the mRNA expression profiles of 1,454 metabolic enzymes across 1,981 tumors covering 19 different tumor types vs. 931 matched normal tissue controls, identify Proline biosynthesis genes (PYCR1 and ALDH18A1) among the most up regulated enzymes." (PMID 32500033, 2020). "While HBB is by far the most abundant transcript differentially expressed between CTCs and primary tumours, we identified 16 other antioxidant genes as being significantly upregulated, including the ALDH family members ALDH9A1 and ALDH18A1, as well as SOD1 and PRDX family members." (PMID 28181495, 2017). "In the ALDH18A1 knockdown group, the protein expression of two well-known EMT-related genes (N-cadherin and Vimentin) and the Epithelial mesenchymal transition (EMT) transcription factor Snail1 decreased, suggesting its suppression of EMT and reduction of tumor cell migration properties." (PMID 38970690, 2024).
cancer (24 papers, 2013 to 2025). A tumor composed of atypical neoplastic, often pleomorphic cells that invade other tissues. "In previous studies, proline metabolism plays a key role in cancer development and progression, and the overexpression of PYCRs and ALDH18A1 has been associated with a poor clinical course." (PMID 35910374, 2022). "In contrast, ALDH1B1, aldehyde dehydrogenase 1 family member L2 (ALDH1L2), and 18 family member A1 (ALDH18A1) are upregulated in most cancers." (PMID 40923024, 2025). "Scant literature exists to link ALDH3B1, ALDH7A1, and ALDH18A1 to cancer, although, these studies provide initial evidence that these isoforms favor tumorigenesis." (PMID 31974410, 2020). "Therefore, a further review of the clinicopathological characteristics, evolution, clinical significance, and drug development prospects of ALDH18A1 and cancers is provided below." (PMID 39051546, 2024). "ALDH18A1 is involved in the generation of a variety of epigenetically regulated intermediates in cancer, such as α-KG100, NAD(P)+57, and SAM101, and plays an important role in metabolic reprogramming and epigenetic regulation of the effects of interconnections in cancer." (PMID 39051546, 2024). "When the expression or activity of ALDH18A1 is altered, other glutamate-related metabolic enzymes in cancer cells may be regulated to compensate for this effect." (PMID 39051546, 2024). "Determining whether these phenotypes occur when targeting ALDH18A1 is very important, and the possible side effects can be mitigated when cancer treatments are targeted." (PMID 39051546, 2024). "Therefore, further exploration of the function of ALDH18A1 in cancers has become increasingly relevant." (PMID 39051546, 2024). "Because it is a crucial enzyme in the glutamine-arginine-proline metabolic system, targeting ALDH18A1 via anticancer therapies could create novel opportunities for cancer intervention." (PMID 39051546, 2024). "Most non-cancer diseases mutations are found in ALDH7A1 and ALDH18A1." (PMID 37373306, 2023). "Three non-cancer pathogenic mutations cluster at Glu427 (aldehyde binding region) of ALDH7A1 and two mutations with the same labels are located at Arg138 (glutamate binding region) of ALDH18A1." (PMID 37373306, 2023). "Additionally, ALDH18A1 has been shown to modulate redox homeostasis, increase resistance to oxidative stress, and promote nucleotide synthesis, all of which are crucial for cancer cell survival and proliferation." (PMID 39858632, 2025). "In conclusion, ALDH18A1 may be a potential drug target for cancer therapy." (PMID 39051546, 2024). "In detail, ALDH9H1, ALDH18A1, ALDH3A2, ALDH1A1, ALDH1B1 and ALDH2 were expressed higher than other ALDH family genes in all cancers." (PMID 34670872, 2021). "Upregulation of the metabolic genes (ALDH18A1, CAD, CHKA, POLD4, PSPH, and SQLE) and aberrant expression of cancer-related genes (ALCAM, ITGA6, DDIT3, MAP3K6, and PAK1) were found in mouse fed with high-fat-high-cholesterol similar to human NASH-HCCs." (PMID 31795276, 2019). "We demonstrated for the first time the aberrant expression of cancer-related genes (ALCAM, ITGA6, DDIT3, MAP3K6 and PAK1) and metabolism-related genes (ALDH18A1, CAD, CHKA, POLD4, PSPH, SQLE and CFD) in human NASH-HCCs." (PMID 30367044, 2018). "An important role of MYC in this process was previously reported in human cancer cell lines, where MYC inhibits PRODH and promotes the transcription of PYCR1 and ALDH18A1." (PMID 29132502, 2017). "Similarly to ALDH18A1, ASPH is also considered an oncogenic enzyme and is overexpressed in various cancers." (PMID 39858632, 2025). "NEAA proline can be synthesized by aldehyde dehydrogenase family 18 member A1 (ALDH18A1, P5CS) and pyrroline-5-carboxylate reductase (PYCR) from glutamine and arginine, thus MYC induced P5CS and PYCR upregulation can promote the proliferation and invasion of cancer cells." (PMID 38218942, 2024).
infection (5 papers, 2012 to 2024). The state of being infected such as from the introduction of a foreign agent such as serum, vaccine, antigenic substance or organism. "In particular, only a few glycolytic/glucanogenic genes exhibited an infection-induced change in expression (PGM2L1, LDHAL6B, ENO3, ALDH8A1, and ALDH18A1)." (PMID 28993767, 2017).